APOE (apolipoprotein E)
Diseases named in the same sentence as APOE in open-access papers (continued):
Sharing a sentence is not in itself a finding about the gene and the disease.
dementia (continued). "Genetic risk factors of dementia by APOE ε4 and MAPT (rs242557) A allele were associated with variations of cortical morphology, which can be observed in young healthy adults more than 30 years before Alzheimer’s pathology is likely to occur and 50 years before dementia symptoms may begin." (PMID 37693814, 2023). "If this observation is confirmed in other studies that found association of low ApoE level with dementia without accounting for the role of HDL subspecies, it may provide new insight into the role of ApoE level in affecting the risk of AD and all-cause of dementia." (PMID 37666928, 2023). "Thus, if the APOE genotypes in each of the included articles can be analyzed, it could be better to understand the relationship between TyG and cognitive impairment or dementia." (PMID 38161596, 2023). "Importantly, certain potentially relevant covariates such as years of education and lifestyle factors such as e smoking habits, regular exercise, and crucially, genetic factors like APOE-ε4, which are associated with dementia risk, were not available in the Korean nationwide cohort data we used." (PMID 37568223, 2023). "By analyzing the association between WMH in the cholinergic pathway and dementia severity among APOE e4 carriers and non-carriers primarily with memory problems, our goal is to examine the potential alterations on WMH that e4 alleles might contribute to in the formation of AD dementia syndrome." (PMID 36864910, 2023). "Dementia is a complex condition with various genetic contributors, in addition to the well-known factors such as familial Alzheimer's disease (FAD) and the APOE gene." (PMID 38074067, 2023). "Even though the healthy pattern in our study also contained food groups that could be included in a western pattern (red meat, desserts, and sweet bakery), we did find an association between higher adherence and reduced risk of dementia among APOE ε4 non-carriers." (PMID 34632537, 2022). "Both APOE genotype and plasma level were strongly associated with risk of dementia (such that e2 had the highest levels and e4/e4 the lowest levels) and genotype accounted for about 0.25 of the variance in plasma ApoE, suggesting that ApoE levels are partially independent of genotype 2." (PMID 35912085, 2022). "Individuals who progressed to MCI or dementia were on average older, had a lower baseline MMSE score, and were more often APOE ε4 carriers." (PMID 35110378, 2022). "Therefore, the present study primarily aimed to verify the role of resting theta rhythm in delayed recall deficits, and further explore the effects of the ApoE genotype on the associations between the resting theta power and delayed recall performance in the elderly individuals without dementia." (PMID 35693343, 2022). "One limitation, however, is that our dataset shows an enrichment of APOE ε4 carriers with MCI and dementia over cognitively normal counterparts." (PMID 35907208, 2022). "We analysed data from a large sample of South Korean participants with subjective cognitive decline (SCD), MCI, and dementia including AD who had amyloid PET scans, apolipoprotein E (APOE) measurements, cognitive testing, and clinical data." (PMID 35974140, 2022). "However, the association between apoE levels and dementia risk does not appear to be linear." (PMID 35751102, 2022). "In this work we establish the significance of the APOE, GBA, MAPT, and SNCA loci on global cognitive decline and the development of dementia over the natural course of PD in the Parkinson’s Incidence Cohorts Collaboration (PICC)." (PMID 35106798, 2022). "The purpose of this study is to investigate the distributions of Apolipoprotein E (APOE) ε4 and geriatric symptoms, and explore their associaitons in Dementia with Lewy bodies (DLB) and Parkinson’s disease dementia (PDD)." (PMID 36123648, 2022).
dementia (continued). "The ApoE status was ɛ2/ɛ3 in the index multiple system atrophy case IV22, ɛ3/ɛ4 in her cousin with Parkinson’s disease with dementia (IV25) and ɛ3/ɛ3 in the other family member with Parkinson’s disease (III12)." (PMID 35855480, 2022). "A measure of weight change was the strongest predictor of future dementia risk from among the risk factors available in the trial (after allowing for age, sex, randomized trial treatment allocation, height, and Townsend index), in the absence of knowledge of cognitive function or APOE genotype." (PMID 36092692, 2022). "Notably, the association between PPI use and dementia was not presented among APOE ε4 homozygotes." (PMID 36045363, 2022). "Since the APOE and TOMM40 genes occupy adjacent loci, it has been shown that both genes influence the pathogenesis of AD and the therapeutic response to anti-dementia treatments." (PMID 35330211, 2022). "The objective of this study was to examine the long-term relationships between amyloid PET, APOE, sex, education and cardiovascular/metabolic conditions (CMC), and two clinically meaningful outcomes—incident dementia and mortality." (PMID 35310829, 2022). "Furthermore, we observed that the relationships between concentrations of AA, ALA, and proportions of EPA and incidence all-cause dementia among APOE ε4 carriers and non-carriers went mostly in the same direction as the main analyses, but the relationships were not significant." (PMID 33573174, 2021). "A total of 302 individuals were included (mean age 73 ± 6.7 years; n = 133 [44%] female; mean level of education 16.1 ± 2.7 years; n = 207 [69%] APOE ε4 carrier), of whom 274 had MCI and 28 mild dementia at first visit." (PMID 34550903, 2021). "The discrepancy between carriers and noncarriers indicates that APOE genotype may modify associations between lifestyle factors and dementia risks, and might be explained by a potential masking of weak associations from lifestyle factors by the strongly associated APOE ε4 allele." (PMID 33748832, 2021). "Here, we report the effects of APOE and PRS on incident dementia and cognitive decline among 12,978 ASPREE participants, where dementia was an exclusionary criterion at entry and adjudicated as a primary trial endpoint." (PMID 34041846, 2021). "In this study, we examined the effect of APOE genotypes and PRS on incident dementia and cognitive decline among 12,978 initially healthy older participants." (PMID 34041846, 2021). "Interestingly, our stratification in dementia, non-dementia, and fatal COVID-19 disease outcome analysis adjusting by age and dementia diagnosis does not corroborate the previous results, suggesting a lack of association of APOE with COVID-19 outcome." (PMID 34945790, 2021). "While APOE does not seem to alter the risk for PD in itself according to GWAS results, the ε4 allele has been studied as a potential risk factor for cognitive decline and development of dementia in PD patients, with several larger studies reporting a significant association." (PMID 33613437, 2021). "Investigational dementia therapies include targeting APOE directly, such as reducing APOE4 expression, with antibodies, anti-sense oligonucleotides, gene therapy, and gene editing." (PMID 33841127, 2021). "The final multivariable models and the SRSS-CNMCI included age, APOE e4, mini mental state examination (MMSE) and clinical dementia rating (CDR)." (PMID 35145390, 2021). "Behavioral disturbances and APOE ε4 are independent factors that, when they converge in MCI patients, manifest themselves most severely predicting conversion to dementia." (PMID 33208795, 2020). "This study contributes to the increasing evidence that brain cholesterol metabolism, ApoE, and TREM2 signaling are major players in the pathogenesis of AD-related dementias, including CAA." (PMID 32711525, 2020).
dementia (continued). "Finally, our results seem to confirm that smoking, already found to be associated with dementia risk in some studies and particularly in apolipoprotein E ε4 noncarriers, may be a risk factor for EOD." (PMID 33138082, 2020). "39% of AD dementia patients, 17% of MCI patients and 10% of healthy individuals were positive for ApoE ε4." (PMID 32741361, 2020). "Cognitively unimpaired individuals were younger, more educated, and had a lower frequency of APOE ε4 than those with MCI and dementia." (PMID 31305929, 2019). "Shu and her colleagues included 837 non-dementia elderly subjects living in the community and found that participants with the rs405509 TT genotype showed worse general cognitive function, attention, and executive function than the G allele carriers, regardless of APOE ε4 state." (PMID 30866553, 2019). "APOE alleles had a different impact: ε4 did not predict dementia, but it did predict all AD- or amyloid-related pathologies; ε2 predicted dementia, but it was protective against amyloid and neuropathological AD; and ε3ε3 was protective against dementia, neurofibrillary tangles, and CAA." (PMID 30670070, 2019). "Indeed, data from the Swedish Kungsholmen Project suggested that APOE ε4 allele was associated with global cognitive decline with subsequent progression to dementia, whereas the association with cognitive decline without progression to dementia was less evident." (PMID 31214016, 2019). "What proportion these severe cases constituted of those who eventually developed dementia and were HSV1-seropositive and APOE-ε4 carriers, is uncertain, though it is probably very low." (PMID 30405395, 2018). "Further, using linear mixed-effect modeling, PHS improved the prediction of change in the Clinical Dementia Rating—Sum of Boxes (CDR-SB) score and MMSE over 36 months in patients with MCI at baseline, beyond both APOE and baseline levels of brain atrophy." (PMID 29760643, 2018). "They found that the APOE ε4 allele was a moderately strong predictor of progression from MCI to AD-type dementia, with a PPV of 0.59 for APOE ε4 homozygotes." (PMID 28373857, 2017). "Thus, it may be the case that APOE influence cognition through pathways not directly linked to the dementia process." (PMID 26252210, 2015). "We observed association of general cognitive function with four genes previously associated with AD or neuropathological features of AD and related dementias (TOMM40, APOE, MEF2C and ABCG1)." (PMID 25644384, 2015). "Conversely, estimates obtained using the AD-GRS excluding APOE found all groups to be similar except NHB males and females for the dementia probability outcome (P = 0.047 for interaction of AD-GRS excluding APOE and gender)." (PMID 25328845, 2014). "Additionally, the finding that the absence of the APOE-ɛ2 allele in study participants in Benin is significantly associated with dementia, and cognitive impairment is unique and calls attention to the role that genes play in the prevalence of dementia in specific SSA populations." (PMID 25177512, 2014). "One possible explanation, that APOE ε4 prolongs survivalwith dementia rather than increasing its incidence, seems unlikely given the weakeffect of APOE genotype on overall survival, and the absence of an interactionbetween dementia status and APOE genotype as risk factors for mortality." (PMID 29213926, 2014). "Despite the fact that APOE ε4 genotype is a risk factor that accelerates degenerative process in the brain (AD), ε4 carrier status alone could not be accountable for cognitive decline or dementia." (PMID 24639912, 2014). "However, common risk factors for dementia (i.e., age, sex, education, family history, and APOE-4) do not predict whether an individual will remain in MCICC or transition to dementia, or death without dementia, at the next visit." (PMID 22536535, 2012).
dementia (continued). "The present study suggests that the effects of the APOE e4 on cognitive functioning might increase in size through the eighth and ninth decades of human life (though it is not definitive on whether the effect is on dementia risk alone or on both that and on non-dementia cognitive decline)." (PMID 41053433, 2026). "Given growing recognition of the need to understand how peripheral dysregulation reflects or contributes to neurodegenerative diseases, we sought to characterize how variation in APOE genotype alters the plasma proteome in elderly subjects without dementia." (PMID 39689057, 2025). "Of them, a colocalized signal (that is, shared single causal variant, PP.H4 > 80%) was detected within APOE and BRAP genes for HFRS, whereas no colocalized signal with pQTL was detected within genes for HFRS without dementia." (PMID 40764432, 2025). "Further investigation with the identified SD-pQTL of APOE and SNAP25 in this study could provide insight into the pathophysiology of dementia and help improve its prediction, diagnosis, and treatment." (PMID 40877285, 2025). "Examination of the highlighted keywords revealed the commonality between HF and dementia, namely IL6, ACE, APOE, APP, ADIPOQ, LEP, and NPPB, suggesting that these proteins may link the two pathologies." (PMID 40699836, 2025). "This approach allowed us to detect increased risk and earlier age of onset for AD and dementia among the monoallelic TYROBP deletion carriers compared to noncarriers, which was not dependent on APOE status." (PMID 40301889, 2025). "Participants with all-cause dementia were more likely to be APOE-e4 carriers, be a childhood smoker, and have lower parental OSC when compared with individuals without all-cause dementia." (PMID 39669703, 2025). "Since most of the identified proteins are not present in both diseases, we performed two independent PPI analyses: the first using the proteins associated with HF (NPPB, REN, ADIPOQ, VWF, ACE, IL6, and CRP) and the second using the proteins involved in dementia (CRP, APP, MAPT, APOE, ACE, and IL6)." (PMID 40699836, 2025). "APOE genotypes, rather than PRS, modified PUFA–dementia associations: individuals with low-to-moderate APOE risk showed greater protective effects of high PUFA levels compared to those with high-risk genotypes." (PMID 40695676, 2025). "There was a significant rise in plasma levels of GFAP, p‐tau217, NfL, apolipoprotein E (APOE) ε4 prevalence, AV45‐PET positivity, and global AV45‐SUVR from the CN group to the MCI group and then to the dementia group, while hippocampal volumes significantly decreased." (PMID 41376134, 2025). "Of 4460 individuals, AD concerns were elevated in women, people with a dementia family history, apolipoprotein E (APOE) ε4 carriers, and individuals who did not meet walking or sleep guidelines." (PMID 40476544, 2025). "Our study, while discovery‐oriented, uniquely highlights changes in the systemic environment in subjects without dementia according to APOE status and brain amyloid status." (PMID 39689057, 2025). "The role of APOE ε4 on PD onset has not been explored extensively in the literature, since most studies have focused on its role toward cognitive decline and dementia onset." (PMID 41180817, 2025). "Univariate Cox regressions found increased risks of developing MCI and dementia for individuals who did not remember dreams, were an APOE e4 carrier, or older than 74 years." (PMID 41001478, 2025). "The study found that, among participants without the apolipoprotein E (ApoE) ɛ4 allele, baseline self-reported SDB was associated with a 66% higher risk of developing dementia at follow-up." (PMID 40782185, 2025). "A proportion of APOE ε4 carriers without dementia still harbor AD pathology, supporting the concept that APOE ε4 confers increased vulnerability long before the onset of overt clinical symptoms." (PMID 41268805, 2025).
dementia (continued). "Lastly, we intended to study AD pathologies (e.g., CERAD, Braak, and APOE e4) as covariates in this study and did not separate out dementia with Lewy bodies and frontotemporal dementia." (PMID 39195563, 2024). "The CAIDE model 2 (including Apolipoprotein E (APOE) ε4 carrier status) predicted all-cause dementia, AD, and VD better than CAIDE model 1 (without APOE ε4) with AUCs of 0.725, 0.752 and 0.707, respectively." (PMID 38570813, 2024). "The prevalence of hypertension, diabetes, chronic kidney disease was similar irrespective of incident dementia diagnosis status, although, APOE e3/e4 and APOE e4/e4 genotype groups were more prevalent in participants with incident dementia." (PMID 38456089, 2024). "Similar to other dementia subtypes, TBI (OR with 95% CI for midlife 6.82 [1.69–27.48] and for late-life OR 6.98 [3.25–14.97]) and APOE e4/e4 genotypes (OR with 95% CI for midlife 3.08 [1.93–4.90] and for late-life OR 4.23 [3.31–5.40]) were among the top risk factors with high odds ratios." (PMID 38807092, 2024). "In the present study, the non-significant interaction between APOE ɛ4 and anti-HSV IgG with regard to the dementia risk was probably due to the lack of power, since the observed effect size was in line with some previous findings." (PMID 38306033, 2024). "As expected, APOE ε4 carriership, clinical dementia rating sum of boxes (CDR SoB), brain Aβ burden, brain tau burden (MetaT) and plasma concentration of pTau217 differed by group and were highest in the dementia group and lowest in the Aβ− CU group." (PMID 39437657, 2024). "APP, APOC1, APOE, SORL1, and MAPT are highly relevant common genes for AD and dementia." (PMID 38790243, 2024). "Recent research points to higher levels of Ng specifically in those with MCI and dementia due to AD who are also APOE ε4 carriers compared to those without ε4, suggesting an influence of APOE in determining Ng levels in the early stages of AD." (PMID 39242539, 2024). "iPSCs donor cohort (no diagnosis of dementia) APOE-ε3/ε3 and APOE- ε4/ε4.CRISPR-edited isogeneic APOE-ε4/ε4 to APOE—ε3/ε3." (PMID 39156632, 2024). "APOE ε4 carriers without dementia exhibit, on average, a more rapid decline in memory, processing speed, and language functions than non-carriers before the age of 60." (PMID 38605018, 2024). "This is supported by studies showing that APOE ε4 carriers exhibit different brain activity patterns in older adults without dementia, possibly reflecting a compensatory mechanism." (PMID 39392181, 2024). "Clinical practice guidelines for dementia in Japan (Japanese Society of Neurology n.d.) published in 2017 have not recommended routine testing of the APOE genotype in daily clinical practice for dementia care in medical facilities." (PMID 38225507, 2024). "Only one previous study examined the interaction between neuroticism and genetic risks, identifying an interaction effect between APOE ε4 and neuroticism on AD (N = 86), but not on non‐AD dementia (N = 12), with up to 7 years of follow‐up." (PMID 38984680, 2024). "Compared to the group without dementia, the group with dementia was more likely to be older, less educated, smokers, APOE ε4 carriers, diagnosed with hypertension, hyperlipidemia, and CVD, and to have higher refractive error and worse visual acuity." (PMID 39868381, 2024). "After adjusting for APOE-ε4, prevalence ratios of dementia for the double and single exposed groups were consistent to our demographic adjusted models without the inclusion of APOE-ε4." (PMID 37323925, 2023). "APOE status was not a central focus of the current review, in favor of differing types of dementia exposure, thus only eight studies included APOE status (Studies 14–16, 18, 24, 27, 29, and 30)." (PMID 37497342, 2023). "In contrast, other studies have reported that higher adherence to both the MIND diet (a hybrid between the MedDiet and Dietary Approach to Stop Hypertension) and a ‘healthy’ diet are more protective against dementia in APOE ε4 non-carriers." (PMID 36915130, 2023).